FGFR2 (fibroblast growth factor receptor 2)
Diseases named in the same sentence as FGFR2 in open-access papers (continued):
Sharing a sentence is not in itself a finding about the gene and the disease.
acne (9 papers, 2019 to 2025). An inflammatory process of the sebaceous glands which is characterized by comedones, nodules, papules and/or pustules on the skin. "Considering that FGFR2 mutations are also associated with acne and that FGFR2 results in the activation of the HS-related PI3K/Akt pathway (caused by mutations in γ-secretase genes), exploration of this aspect could be relevant." (PMID 31105704, 2019). "In some cases of NC, a somatic missense mutation in FGFR2 (Fibroblast Growth Factor-Receptor gene 2) gene has been identified; this gene is mainly expressed in keratinocytes, hair follicles, and sebaceous glands and is considered as a central player in the pathophysiology of acne vulgaris." (PMID 36009585, 2022). "This latter syndromic association between androgens, FGFR2, acne, and alopecia raises the intriguing hypothesis that in addition to FGFR2b-induced inflammatory folliculitis, androgen-dependent FGFR2b proapoptotic signaling could be involved in the pathogenesis of male-pattern baldness." (PMID 34007277, 2021). "This dual modulation of FGFR2/AR signaling underscores the potential of HA derivatives as safe, biologically active agents for acne treatment." (PMID 41471115, 2025). "In preclinical models, HA-P5 nanoparticles simultaneously suppressed fibroblast growth factor receptor-2 (FGFR2) and androgen receptor (AR) signaling in sebocytes, reduced sebum synthesis, and reversed acne-associated transcriptomic alterations." (PMID 41471115, 2025). "Previous studies demonstrated P5’s anti-inflammatory and anti-fibrotic effects in acne and cancer models, primarily through its inhibition of FGFR2 signaling." (PMID 39859240, 2025). "In our previous research, we demonstrated that P5 inhibits FGFR2 and androgen receptor (AR) signaling, suggesting its potential as an acne antagonist." (PMID 39859240, 2025). "Further studies subsequently demonstrated that FGFR2 mutants with constitutive activity contributed to systemic acne lesions in patients." (PMID 36803994, 2023). "Our findings highlighted HA-P5 as an optimized FGFR2 inhibitor for acne treatment and uncovered a potential mechanism by which FGFR2 regulates AR signalling." (PMID 36803994, 2023). "Overall, we demonstrate that a polysaccharide-conjugated and naturally derived oligopeptide HA-P5 can alleviate acne and act as an optimal FGFR2 inhibitor and reveal that YTHDF3 plays a crucial role in signalling between FGFR2 and AR." (PMID 36803994, 2023). "Relevant to cancer control, acne is inducible not only by Apert-like mutagenic FGFR2 activation but also by epidermal growth factor receptor (EGFR) inactivation, either by homozygous knockout or targeted drug inhibition." (PMID 34007277, 2021). "A direct genotype-phenotype relationship between acne and FGFR2 expression has been confirmed in postzygotic FGFR2 mosaics and in segmental acneiform nevi." (PMID 34007277, 2021). "Consistent with this, prevention of EGFR inhibitor-induced acne by skin irradiation is attributable to FGFR2 downregulation; FGF7-activated FGFR2b causes TGFα-induced EGFR signaling, completing a homeostatic FGFR2-EGFR control loop." (PMID 34007277, 2021). "Therefore, FGFR2 signalling is closely related to the prognosis of acne therapy." (PMID 36803994, 2023). "Moreover, hyperactivated FGFR2 further drives the progression of acne lesions." (PMID 36803994, 2023). "In skin tissues suffering from acne, AR signalling triggers the transcription of two FGFR2 ligands, FGF-7 (also known as keratinocyte growth factor, KGF) and FGF-10, which results in the activation of FGFR2 signalling." (PMID 36803994, 2023). "Moreover, our results show that HA-P5 inhibits both fibroblast growth factor receptor 2 (FGFR2) and androgen receptor (AR) signalling in SZ95 cells, reverses the acne-prone transcriptome, and decreases sebum secretion." (PMID 36803994, 2023).
acne (continued). "Pharmacologic EGFR inhibition in nonresistant CRCs is associated with compensatory FGFR2-induced p38/MAPK upregulation that induces the downstream proinflammatory mesenchymal mitogen IL-1α which in turn promotes both sporadic acne and iatrogenic folliculitis." (PMID 34007277, 2021).
Beare-Stevenson syndrome (9 papers, 2006 to 2025). "Beare-Stevenson syndrome is caused by FGFR2 gene mutations and it is characterized by simplified gyroscopic patterns." (PMID 39735065, 2024). "On WGS, a de novo pathogenic FGFR2 variant (p.Y375C) was identified, diagnosing Beare-Stevenson syndrome, conferring a greatly reduced reproductive recurrence risk compared to the suspected AR disorder." (PMID 35970915, 2022).
depression (9 papers, 2018 to 2025). "FGFR2 belongs to the fibroblast growth factor family, which is a widely researched system that has been associated with depression as well as stress response and anxiety." (PMID 35697758, 2022). "Of thirteen depression‐associated DRPs, seven proteins including DDC, FGFR2, KIBRA, MED22, OLIG1, RAI1, SLIT2 were upregulated, whereas six proteins including COX3, CRHBP, CSMD1, FSTL1, GRIK4, and LMTK3 were downregulated." (PMID 39373701, 2024). "DUSP22 was also related to schizophrenia, ZFP57 with autism, and FGFR2 with depression." (PMID 36091392, 2022). "However, to date no published study have reported the association between FGF20 gene and depression; although some studies have reported association between another FGF system transcripts, such as FGF2, FGF12 and FGFR2 with major depressive disorder." (PMID 30241547, 2018). "On the contrary, no SNPs of FGFR2 gene was associated with depression." (PMID 30804785, 2019). "By contrast, the upregulation of DDC, FGFR2, KIBRA, and MED22, and the downregulation of FSTL1, GRIK4, and LMTK3 in the RagA transgenic mice were negatively correlated with depression." (PMID 39373701, 2024). "However, another study found decreased expression of FGFR2 and FGFR3 in the dorsolateral prefrontal cortex (DLPFC) and the anterior cingulate cortex (AnCg) after autopsy on patients with depression." (PMID 30804785, 2019).
diabetes (9 papers, 2014 to 2024). "Indicative of a dysfunctional signaling environment in situ, the expression of multiple growth factors and cytokines (Vegf-a, Fgf-2, Pdfg-a, and Sdf-1; P <0.02) as well their associated receptors (Cxcr-4, Fgfr-2, and Pdgfr-a; P <0.01) was significantly decreased in the setting of diabetes." (PMID 24943716, 2014). "MET signaling may promote cancer recurrence as well as insulin resistance and diabetes; the WNT pathway could be associated with adipocyte hyperplasia, diabetes, and metabolic disorders; and FGFR2 transduction signaling also may play a role in obesity, adipocyte hyperplasia, and cancer." (PMID 33361524, 2020). "Finally, we identified that the targets of Nintedanib, specifically Fgfr1 and Fgfr2, are indeed upregulated in individuals with hypertension and diabetes." (PMID 38144556, 2023). "FGFR2 associated with obesity and weight at birth and with adult obesity; DUSP22 related to diabetes and obesity, and ZFP57 related to nutrition/neonatal diabetes." (PMID 36091392, 2022). "After Addmodule Score analysis, Fgfr1 and Fgfr2 were increased in hypertension as well as hypertension-diabetes, respectively, but no significant changes were seen in TGF-b1, TGF-b2, and TGF-b3, the targets of Pirfenidone." (PMID 38144556, 2023). "Of note, FGFR2 expression correlated significantly with neonatal sum of skinfolds and placental weight, which accords with a previous report showing a positive relationship between FGF2 and birth-weight and placental size in pregnancies complicated by diabetes." (PMID 34930438, 2021).
esophageal cancer (9 papers, 2015 to 2025). A primary or metastatic malignant neoplasm involving the esophagus. "This is not true for Her2/neu amplification in upper GIT adenocarcinomas and, as we have shown in the present study, for FGFR2 amplification in gastric and esophageal cancer." (PMID 36416959, 2023). "Partial response was confirmed in one patient with FGFR1-mutant esophageal carcinoma and one with FGFR2-mutant cholagiocarcinoma." (PMID 37889382, 2023). "In accordance with our results, have shown FGFR2 are able to promote tumor development and progression in esophageal carcinoma and FOXP1, as a member of Forkhead-box (FOX) family genes, was reported to be associated with poor prognosis of multi-cancer." (PMID 27331408, 2016).
leukemia (9 papers, 2017 to 2024). A malignant (clonal) hematologic disorder, involving hematopoietic stem cells and characterized by the presence of primitive or atypical myeloid or lymphoid cells in the bone marrow and the blood. "FGFR1 and 2, the receptor of FGF2, were differently expressed in leukaemia cells co-cultured with MSCs from different origin and FGFR2 expression was significantly increased in leukaemia cells co-cultured with MSCs from T-ALL mice after PCR validation." (PMID 36333298, 2022). "We also show that stimulation of leukemia cells with FGF2 increases nuclear level of FGFR2 in its phosphorylated form, as well as HOXA9 and MEIS1 expression." (PMID 33924850, 2021). "In agreement with the previous evidence that reduced expression of HOXA9 and MEIS1 impairs viability of leukemia cells, FGFR2 knockdown negatively affected the proliferative rate of RS4;11 leukemia cells." (PMID 33924850, 2021). "However, after addition of BGJ398 or FGF2 knockdown, the expression of phosphorylation of PI3K/AKT/mTOR proteins were significantly reduced, indicating that FGF2/FGFR2 combination activated PI3K/AKT/mTOR pathway in leukaemia cells." (PMID 36333298, 2022). "Therefore, we carried out coimmunoprecipitation experiments in RS4;11 and MV4-11 leukemia cells and found that endogenous FGFR2 interacted with endogenous MLL-AF4." (PMID 33924850, 2021). "Two ways were used to block the interaction between FGF2 and FGFR2: one way used shRNA to knockdown FGF2 in MSCs, the other way was FGFR inhibitor BGJ398 to competitively combined with FGFR2 in leukaemia cells." (PMID 36333298, 2022). "To further support the evidence that FGFR2 activation and nuclear translocation were ligand-dependent, we treated RS4;11 leukemia cells with PD173074, a synthetic compound belonging to the pyrido (2,3-d) pyrimidine class." (PMID 33924850, 2021). "Treatment of leukemia cells with the PD173074 inhibitor, which binds the ATP pocket of FGFR2, prevents FGF2-mediated nuclear entry of pFGFR2 and, consequently, also transcriptional activation of MLL-AF4 target genes." (PMID 33924850, 2021). "Based on our overall results, we propose a model illustrating how nuclear cross-talk between FGFR2 and MLL-AF4 promotes aberrant transcription of MLL-AF4 target genes in leukemia cells." (PMID 33924850, 2021). "Due to the molecular heterogeneity in AML, genetic abnormalities can vary between individual cases of leukemia, and there may be rare cases where JAK1, PDGFRA and FGFR2 abnormalities are present in CBF-AML." (PMID 37509244, 2023). "RNA sequence results revealed that T-ALL derived MSCs secreted fibroblast growth factor 2 (FGF2), which combined with fibroblast growth factor receptor 2 (FGFR2) on leukaemia cells, resulting in activation of PI3K/AKT/mTOR signalling pathway in leukaemia cells." (PMID 36333298, 2022).
osteoporosis (9 papers, 2015 to 2025). A condition of reduced bone mass, with decreased cortical thickness and a decrease in the number and size of the trabeculae of cancellous bone (but normal chemical composition), resulting in increased fracture incidence. "Herein we describe a patient with bone fragility and severe early-onset osteoporosis carrying a likely mosaic pathogenic variant in FGFR2." (PMID 40362441, 2025). "Recently, Dantsev and colleagues reported the case of a 13-year-old boy affected by osteoporosis and multiple fractures, with a family history of abnormal bone mineralization and fractures, carrying a heterozygous variant in the FGFR2 gene." (PMID 40362441, 2025). "A report recently identified FGFR2 as a potential cause of dominant early-onset osteoporosis and bone fractures in a family." (PMID 40362441, 2025). "Here, we describe the case of a child with severe osteoporosis and multiple fractures, carrying a likely mosaic pathogenic FGFR2 variant." (PMID 40362441, 2025). "One of the candidate genes, the pathogenic variants in which are involved in the pathogenesis of osteoporosis is FGFR2." (PMID 38098042, 2023). "Moreover, recent population studies have suggested an association between FGFR2 variants and increased susceptibility to osteoporosis, further highlighting its contribution to bone homeostasis." (PMID 40362441, 2025). "The available clinical and genetic data indicate that pathogenic variants in the FGFR2 gene could be linked to a new phenotype of early onset osteoporosis with bone deformities and fractures." (PMID 38098042, 2023). "Therefore, having analyzed the case of early-onset osteoporosis with bone fractures, as well as available scientific data, we consider it likely that pathogenic variants in FGFR2 can lead to the development of a bone mineralization disorder, specifically associated with an earlier age of onset." (PMID 38098042, 2023). "FGFR2 (rs199545667, rs4752570) were linked to HTN and osteoporosis, and to height and HTN; FGFR4 (rs351855), a missense variant, was linked to HTN and height." (PMID 41573461, 2025). "Our findings provide further evidence that FGFR2 pathogenic variants can lead to a novel non-syndromic bone mineralization disorder, reinforcing the role of FGFR2 in the pathogenesis of early-onset osteoporosis." (PMID 40362441, 2025). "Taken together, our results suggest that OTUB1 positively regulates osteogenic differentiation and mineralization in bone homeostasis by controlling FGFR2 stability, which provides an optical therapeutic strategy to alleviate osteoporosis." (PMID 37024477, 2023). "LIN00472 alleviates osteoporosis by upregulating FGFR2 expression by sponge miR-300 to regulate osteoblast differentiation." (PMID 34753389, 2021). "WNT1 encodes a key protein in bone development and bone mass; therefore, we speculate that the involvement of FGFR2 in WNT signaling in bone tissue could lead to an osteoporosis phenotype." (PMID 40362441, 2025). "Additional studies aimed at better characterizing bone density and architecture in more patients with FGFR2-related osteoporosis— for example, using high-resolution peripheral quantitative computed tomography—could help to define this new condition." (PMID 40362441, 2025). "FGFR2 destabilization leads to osteoporosis, which is partially rescued by FGFR2 re-expression." (PMID 37024477, 2023). "A deeper understanding of the molecular mechanism by which FGFR2 contributes to osteoporosis could pave the way for identifying novel therapeutic targets for skeletal disorders characterized by bone fragility or multifactorial osteoporosis." (PMID 40362441, 2025). "However, the role of FGFR2 in the pathogenetic mechanism of osteoporosis needs further research." (PMID 38098042, 2023).
osteoporosis (continued). "In mouse BMSCs, miR-338-3p that directly affect Runx2 and fibroblast growth factor receptor 2 (Fgfr2) serves as a negative regulator of osteogenic differentiation and may also contribute to osteoporosis, which was shown up-regulated in ovariectomized (OVX) mice compared with sham mice." (PMID 25872144, 2015). "In this study, we unveil the positive role of OTUB1 in osteoblast-mediated bone formation by maintaining FGFR2 stability and the osteogenesis effects of OTUB1 provide an optical therapeutic strategy to alleviate osteoporosis." (PMID 37024477, 2023). "In fact, in the revised nosology, FGFR2-related conditions are classified as “Craniosynostosis disorders” or “Bent bone disorders”, but not under “Osteogenesis Imperfecta and bone fragility”, as osteoporosis and bone fractures are not major clinical findings in FGFR2-related diseases." (PMID 40362441, 2025).
pancreatic ductal adenocarcinoma (9 papers, 2008 to 2025). An infiltrating adenocarcinoma that arises from the epithelial cells of the pancreas. "The proposed methodology was validated using two well-established kinases, FGFR2 and IGF1R, whose roles have been linked in various pathological conditions (e.g., pancreatic ductal adenocarcinoma, PDAC)." (PMID 40362694, 2025). "FGFR2 was highly expressed in many pancreatic ductal adenocarcinoma (PDAC) tissues, and knockdown of FGFR2 IIIb and IIIc in PDAC cells inhibited cell proliferation, migration, invasion, and in vivo tumor formation." (PMID 33801580, 2021). "High levels of FGFR-2 IIIC isoform, mostly expressed in mesenchymal cells, contributed to disease aggressiveness in pancreatic ductal adenocarcinoma and imparted pancreatic tumour cells with cancer stem cell features." (PMID 38473753, 2024). "Notably, ATP6V0D1 deletion exerted distinct effects in pancreatic ductal adenocarcinoma (PDAC) models, differentiating FGFR2-dependent from FGFR2-independent (MIAPaCa2) subtypes." (PMID 41019981, 2025).
sarcoma (9 papers, 2013 to 2026). A usually aggressive malignant neoplasm of the soft tissue or bone. "Of the 21 patients with FGFR2 amplification, 18 (85.7%) had GC, followed by sarcoma (N = 2, 9.5%) and CRC (N = 1, 4.8%)." (PMID 35342406, 2022). "This analysis revealed that the majority of SNF5-deleted rhabdoid tumors express elevated levels of FGFR2 compared to the bulk of sarcoma samples." (PMID 24204904, 2013). "Upon disease progression, she was enrolled on a clinical study with the multi-kinase inhibitor pazopanib that is FDA-approved for the treatment of advanced renal cancer or sarcoma – and fortuitously has nanomolar activity against FGFR2 (in vitro IC50 to FGFR2≈350 nM)." (PMID 24550739, 2014). "In pediatric sarcoma databases, the rates of alterations of the FGFR1, FGFR2, FGFR3, and FGFR4 genes were 1.3%, 0.2%, 0.2%, and 2.4%, respectively, while in neuroblastoma tumor samples, the rates of alterations were 0.2% for each." (PMID 40510032, 2025). "While we did not observe any effects on FGFR expression upon SNF5-knockdown in the sarcoma cell lines tested, we found that in BJ cells knockdown of SNF5 led to increased mRNA levels of FGFR2." (PMID 24204904, 2013). "In addition, by means of qRT-PCR we confirmed the elevated levels of FGFR1 or FGFR2 transcript in the MRT cells in comparison to two non-FGFR-dependent sarcoma lines, SK-LMS1 and SK-UT-1." (PMID 24204904, 2013). "We tested the effect of siRNA-mediated SNF5-knockdown in a panel of non-MRT sarcoma cell lines with low or moderate FGFR1 and FGFR2 levels, as well as in BJ cells, a non-immortalized human fibroblast line, previously reported to have a functional SWI/SNF complex." (PMID 24204904, 2013).